OTUD5 (OTU deubiquitinase 5)
Description:
Deubiquitinating enzyme that functions as a negative regulator of the innate immune system. Has peptidase activity towards 'Lys-48'- and 'Lys-63'-linked polyubiquitin chains. Can also cleave 'Lys-11'-linked ubiquitin chains (in vitro). Acts via TRAF3 deubiquitination and subsequent suppression of type I interferon (IFN) production. Controls neuroectodermal differentiation through cleaving 'Lys-48'-linked ubiquitin chains to counteract degradation of select chromatin regulators such as ARID1A, HDAC2 and HCF1. Acts as a positive regulator of mTORC1 and mTORC2 signaling following phosphorylation by MTOR: acts by mediating deubiquitination of BTRC, leading to its stability.
Synonyms: DUBA; DKFZp761A052; MCAND
Tractability: PROTAC: ubiquitination databases record sites on it.
Target class: Enzyme; Hydrolase
Gene: Protein-coding gene on chromosome X (48,922,024 to 48,958,386, reverse strand). Ensembl gene ENSG00000068308.
Subcellular location: Nucleus
Subcellular location (Human Protein Atlas): Cytosol; Nucleoli fibrillar center; Nucleoplasm
Pathways (Reactome):
Immune System: Negative regulators of DDX58/IFIH1 signaling
Metabolism of proteins: Ovarian tumor domain proteases
Gene Ontology:
Molecular function: cysteine-type deubiquitinase activity; deubiquitinase activity; K48-linked deubiquitinase activity; K63-linked deubiquitinase activity
Biological process: negative regulation of canonical Wnt signaling pathway; neural crest cell differentiation; positive regulation of TORC1 signaling; positive regulation of TORC2 signaling; protein deubiquitination; protein K48-linked deubiquitination; protein K63-linked deubiquitination; response to lipopolysaccharide; negative regulation of type I interferon production; regulation of immune response; cell differentiation; negative regulation of cytokine production
Cellular component: nucleus; cytosol
Gene-disease validity (ClinGen):
ClinGen rates the evidence that OTUD5 causes each of these diseases.
multiple congenital anomalies-neurodevelopmental syndrome, X-linked (X-linked): Moderate.
Homologues: Orthologues: macaque OTUD5 (99% identical), rabbit OTUD5 (99% identical), dog OTUD5 (99% identical), guinea pig OTUD5 (99% identical), pig OTUD5 (99% identical), rat Otud5 (99% identical), mouse Otud5 (98% identical), chimpanzee OTUD5 (92% identical), zebrafish otud5a (72% identical), zebrafish otud5b (64% identical), Drosophila melanogaster Duba (32% identical), Caenorhabditis elegans otub-4 (28% identical). Paralogues in human: OTUD4 (21% identical), OTUD3 (14% identical), OTUD1 (12% identical), OTUD6B (9% identical), OTUD6A (8% identical).
Diseases named in the same sentence as OTUD5 in open-access papers:
OTUD5 is named in the same sentence as 51 diseases in open-access papers, as found by Europe PMC text mining. Sharing a sentence is not in itself a finding about the gene and the disease. The quoted sentences say what the papers report.
breast carcinoma (7 papers, 2022 to 2025). "In breast cancer (BC), OTUD5, YOD1, OTUD6A, OTUD7B, ZRANB1, and TNFAIP3 were characterized as carcinogenic drivers." (PMID 40469292, 2025). "In breast cancer, OTUD5 deubiquitinates and stabilizes YAP in macrophages, and YAP promotes M2 macrophage polarization, which is beneficial for enhancing the metastatic ability of breast cancer cells." (PMID 38658981, 2024). "As UCHL1, OTUD5 demonstrated oncogenic roles in colon cancer and breast cancer, and suppressing features in HCC and cervical cancer." (PMID 38918720, 2024). "In breast cancer and colon cancer, OTUD5 promotes carcinogenesis by regulating the mammalian target of rapamycin (mTOR) and Hippo signaling pathways." (PMID 37190070, 2023). "We also took our RNA-Seq data into consideration, including proteases like OTUD5, which was significantly upregulated in all three breast cancer cell lines, or Cathepsin A that was significantly upregulated in MCF7 and MDA-MB-231 cells." (PMID 35673573, 2022). "(B) Volcano plot analysis of SIAH2 DBC1 and OTUD5 expression levels in breast cancer." (PMID 35913115, 2022). "In addition, OTUD5 knockdown has been shown to inhibit the proliferation of cancer cell lines with mutations that activate the mTOR pathway; these include HT29 colon cancer cells and MCF7 breast cancer cells." (PMID 37190070, 2023). "In breast cancer, for instance, OTUB1, YOD1, OTUD5, OTULIN, TNFAIP3, and ZRANB1 drove chemoresistance, whereas OTUD1 and OTUD3 were sensitized to chemotherapy." (PMID 40469292, 2025). "OTU deubiquitinase 5 (OTUD5), a DUB family member, has been recognized as a critical regulator in bladder cancer, breast cancer and HCC." (PMID 38658981, 2024).
cervical cancer (7 papers, 2020 to 2025). A primary or metastatic malignant neoplasm involving the cervix. "The results also suggested that low OTUD5 expression was associated with the poor prognosis in other types of tumors (pancreatic cancer, cervical cancer, etc.), but the function of OTUD5 in other types of tumors remains to be clarified." (PMID 32248621, 2020). "Taken together, the low expression of OTUD5 is associated with poor prognosis in cervical cancer and OTUD5 is a potential tumor suppressor gene." (PMID 32655987, 2020). "The low expression of OTUD5 is associated with a poor prognosis for cervical cancer." (PMID 37190070, 2023). "OTUD5 copy number, mRNA and mutations all may affect its expression in cervical cancer, and regulate the progression of tumors." (PMID 32655987, 2020). "Here, we found that low expression of OTUD5 in cervical cancer is associated with poor prognosis." (PMID 32655987, 2020). "In addition, OTUD5 undergoes mutational inactivation and loss of copy number in cervical cancer tissues." (PMID 32655987, 2020). "OTUD5 reduces the level of AKT phosphorylation activation through deubiquitination to increase the sensitivity of cervical cancer to radiotherapy." (PMID 41050073, 2025). "In bladder, breast and cervical cancers, OTUD5 exhibits pro‐carcinogenic effects, whereas in lung and liver cancers, it plays an anti‐carcinogenic role." (PMID 40070026, 2025). "In cervical cancer, low expression of OTUD5 was positively correlated with tumor stage, lymph node metastasis, and poor prognosis." (PMID 41050073, 2025). "OTUD5 overexpression has been shown to significantly downregulate the phosphorylation level of Akt in cervical cancer cells." (PMID 37190070, 2023). "In accordance, OTUD5 is also negatively correlated with clinicopathologic characteristics of liver and cervical cancers." (PMID 35765958, 2022). "To identify the upstream molecules that regulate the mRNA levels of OTUD5 in cervical cancer, we analyzed miRNAs and transcription factors related to OTUD5." (PMID 32655987, 2020). "To detect the role of OTUD5 in cervical cancer, we first analyzed the survival rate and OTUD5 expression in cervical cancer patients." (PMID 32655987, 2020). "In summary, through bioinformatics analysis, we obtained a comprehensive view of the role of OTUD5 in cervical cancer." (PMID 32655987, 2020). "Our study for the first time analyzed the expression of OTUD5 in cervical cancer and its relationship with clinicopathology and provided new insights for further study of its regulatory mechanism in tumors." (PMID 32655987, 2020). "In the present study, we found that reduced expression of OTUD5 is correlated with poor prognosis in cervical cancer." (PMID 32655987, 2020). "In cervical cancer, OTUD5 also plays an important oncogenic function." (PMID 37190070, 2023). "Our analysis suggested that although OTUD5 is methylated in cervical cancer, its coexpressed genes may affect the progression of cervical cancer by regulating methylation." (PMID 32655987, 2020). "The new regulatory relationship between miRNA and OTUD5 may be involved in the regulatory network of the Hippo pathway in cervical cancer." (PMID 32655987, 2020). "In addition, OTUD5 was significantly underexpressed in cervical cancer cell lines(HT-3 and DoTc2-4510) according to COSMIC database analysis." (PMID 32655987, 2020). "A recent study demonstrated that OTUD5 could increase the radiosensitivity of cervical cancer cells, which was consistent with the results of this study." (PMID 32248621, 2020). "The expression of OTUD5 in cervical cancer tissues was lower than that in normal tissues." (PMID 32655987, 2020). "OTUD5 and its coexpressed genes may regulate the ubiquitination of proteins and affect the occurrence and development of cervical cancer." (PMID 32655987, 2020). "In addition, mir-137, mir-144, mir-607, mir-937, mir-1913 and mir-3149 could inhibit the expression of OTUD5 in cervical cancer." (PMID 37190070, 2023).
cervical cancer (continued). "Interestingly, OTUD5 overexpression also significantly downregulated the ubiquitination level of Akt in cervical cancer cells, suggesting that OTUD5 may be a deubiquitinating enzyme for Akt." (PMID 37190070, 2023). "OTUD5 may regulate the occurrence or metastasis of cervical cancer through its interacting protein." (PMID 32655987, 2020). "Therefore, we speculated that transcription factors may affect the expression of OTUD5 in cervical cancer." (PMID 32655987, 2020). "Therefore, these miRNAs may influence the prognosis of cervical cancer by regulating the expression of OTUD5." (PMID 32655987, 2020). "OTUD5 expression has been reported to be significantly upregulated in bladder cancer and downregulated in HCC, cervical cancer and NSCLC." (PMID 37190070, 2023).
ovarian tumor (7 papers, 2013 to 2025). "The OTUD5 gene at Xp11.23 encodes ovarian tumor deubiquitinase 5 protein, which is a deubiquitinating enzyme member of the ovarian tumor family." (PMID 33748114, 2021). "OTUD5 (OTU Deubiquitinase 5) is a functional cysteine protease with deubiquitinase activity and is a member of the ovarian tumor protease (OTU) family." (PMID 37190070, 2023). "In cardiomyocytes, 4‐HNE blocks the interaction between glutathione peroxidase 4 (GPX4) and ovarian tumor (OTU) deubiquitinase 5 (OTUD5) by addition and carbonylation, which promotes GPX4 ubiquitination and degradation." (PMID 37552043, 2023). "Ovarian tumor protease deubiquitinase 5 (OTUD5) has been discussed as a regulator of cancer development." (PMID 35765958, 2022). "OTUD5, a deubiquitinating enzyme from the OTU family, is composed of 571 amino acids and contains two key domains: an ovarian tumor domain and a ubiquitin-interacting motif." (PMID 40156957, 2025).
bladder cancer (6 papers, 2022 to 2025). "In bladder cancer, OTUD5 has been shown that is highly expressed in tumor tissues compared with normal urothelial cells." (PMID 37497216, 2023). "Everolimus treatment, an mTOR inhibitor, with simultaneous OTUD5 knockdown seems to be an ideal strategy for bladder cancer treatment." (PMID 37497216, 2023). "In this study, we proved that OTUD5 is involved in the progression of bladder cancer and exerts its cancer-promoting effect by activating mTORC1 signaling." (PMID 36085200, 2022). "In this study, we first discovered that OTUD5 as an oncogene promotes the progression of bladder cancer." (PMID 36085200, 2022). "Here, we report that the deubiquitinating enzyme, ovarian tumor domain-containing protein 5 (OTUD5), can activate the mTOR signaling pathway, promote cancer progression, and show its oncogenic potential in bladder cancer." (PMID 36085200, 2022). "To explore the role of OTUD5 in bladder cancer, we first performed immunohistochemical analysis of tissue samples from patients with bladder cancer." (PMID 36085200, 2022). "Next, we investigated the role of OTUD5 in bladder cancer by constructing cell lines with stable OTUD5 knockdown and overexpression." (PMID 36085200, 2022). "Taken together, these results indicate that OTUD5 can promote tumor proliferation in bladder cancer." (PMID 36085200, 2022). "First, we investigated the in vitro inhibitory effect of OTUD5 knockdown combined with everolimus on the proliferation of bladder cancer cells." (PMID 36085200, 2022). "The result showed significantly higher OTUD5 expression in bladder cancer tissues compared with the adjacent tissues." (PMID 36085200, 2022). "Compared with that in normal bladder epithelial cells, OTUD5 mRNA and protein showed a trend of overexpression in bladder cancer cell lines." (PMID 36085200, 2022). "Next, we investigated the relationship between p-mTOR and OTUD5 in bladder cancer tissues using immunohistochemistry." (PMID 36085200, 2022). "However, some related studies have reported that OTUD5 acts as an oncogene in bladder cancer and triple-negative breast cancer (TNBC)." (PMID 41050073, 2025). "In addition, OTUD5 knockdown also enhances the sensitivity of bladder cancer cells to everolimus, an inhibitor of mTOR." (PMID 41050073, 2025). "The deubiquitinase OTUD5 regulates mTOR signaling and promotes bladder cancer progression." (PMID 37190070, 2023). "In addition, Western blot and immunohistochemistry found overexpressed OTUD5 in cancer tissues obtained from bladder cancer patients." (PMID 36085200, 2022). "Furthermore, we investigated the function of OTUD5 in bladder cancer and found that OTUD5 can promote the proliferation of bladder cancer cells." (PMID 36085200, 2022). "Additionally, we analysed the expression of OTUD5 in paired samples of bladder cancer tissues and normal bladder tissues from 12 patients through Western blot." (PMID 36085200, 2022). "However, there are few reports addressing the function of OTUD5 in tumorigenesis, especially in bladder cancer." (PMID 36085200, 2022). "In summary, our research first discovered that OTUD5 plays an oncogenic role in bladder cancer." (PMID 36085200, 2022). "Interestingly, the combination of OTUD5 knockdown and everolimus showed a more significant inhibitory effect on bladder cancer cell proliferation than the everolimus treatment alone." (PMID 36085200, 2022). "Our previous results have shown that OTUD5 can promote the proliferation of bladder cancer cells." (PMID 36085200, 2022). "The result once again showed increased OTUD5 expression in bladder cancer tissues." (PMID 36085200, 2022). "In addition, bladder cancer cells and transplanted tumors with OTUD5 knockdown are more sensitive to the mTOR inhibitor everolimus, which provides new ideas for personalized treatment of bladder cancer patients in the future." (PMID 36085200, 2022).
bladder cancer (continued). "Moreover, the various inhibition effects in bladder cancer cells with different levels of OTUD5 expression may provide new insights into the treatment of bladder cancer in the future." (PMID 36085200, 2022). "OTUD5 is poorly expressed in HCC and non-small cell lung cancer (NSCLC), while its overexpression is observed in bladder cancer." (PMID 38658981, 2024). "OTUD5 can activate the mTOR signalling pathway by deubiquitinating ring finger protein 186 (RNF186), thereby promoting the progression of bladder cancer." (PMID 38658981, 2024). "This study provides new ideas for personalized treatment of bladder cancer patients, but the lack of specific inhibitors for OTUD5 does not allow an in-depth analysis of the therapeutic effects of OTUD5 inhibitors combined with everolimus." (PMID 41050073, 2025). "Furthermore, Western blot and RT-PCR analyses showed increased OTUD5 expression in bladder cancer cell lines (RT4, 5637, UM-UC-14 and 253 J, not including T24) compared with the urothelial cell line SV-HUC." (PMID 36085200, 2022). "Though the everolimus treatment with a simultaneous OTUD5 knockdown seems to be an ideal strategy, there is currently no specific inhibitor for OTUD5, and future discoveries of OTUD5 inhibitors may lead to some more effective bladder cancer treatments." (PMID 36085200, 2022).
hepatocellular carcinoma (4 papers, 2023 to 2025). A malignant tumor that arises from hepatocytes. "An analysis of clinical samples revealed that OTUD5 expression is significantly downregulated in hepatocellular carcinoma and non-small cell lung cancer." (PMID 37190070, 2023).
non-small cell lung carcinoma (4 papers, 2020 to 2024). A group of at least three distinct histological types of lung cancer, including non-small cell squamous cell carcinoma, adenocarcinoma, and large cell carcinoma. "Herein, the present study set out to explore the molecular mechanism of OTUD5 in non-small cell lung cancer (NSCLC) cell proliferation, invasion, and migration." (PMID 35765958, 2022). "To further validate OTUD5 roles in tumor suppression, we investigated the OTUD5 expression and clinical significance in human non-small-cell lung carcinoma (NSCLC)." (PMID 32826889, 2020).
colitis (3 papers, 2021 to 2025). Inflammation of the colon. "The siRNA-mediated knockdown of Otud5 resulted in the development of severe DSS-induced colitis even with MDP activation of NOD2 through the upregulation of colonic expression of IFN-α and CXCL10." (PMID 41155222, 2025). "Regarding the molecular mechanisms underlying the suppression of DSS- and CpG-induced severe colitis by MDP activation of NOD2, OTUD5 expression was markedly increased in the colons of mice treated with MDP and CpG." (PMID 41155222, 2025). "Collectively, these in vitro and in vivo studies strongly suggest that MDP activation of NOD2 inhibits TLR9-induced type I IFN responses through the removal of the K63-linked polyubiquitination of TRAF3 by OTUD5 activation, and thereby suppresses the development of TLR9-induced colitis." (PMID 41155222, 2025). "Recently, OTUD5 was found to be up-regulated in the intestinal inflammatory tissues of IBD patients and TNBS-induced colitis mice, and IFN-γ was found to up-regulate OTUD5’s expression through a p38/MAPK-dependent mechanism." (PMID 34956195, 2021).
inflammatory bowel disease (3 papers, 2023 to 2025). A spectrum of small and large bowel inflammatory diseases of unknown etiology. "It has been found that IFN-γ stimulation increases OTUD5 expression in LPMC from patients with inflammatory bowel disease." (PMID 37190070, 2023). "Thus, it is possible that OTUD5 is also involved in the amplification of abnormal cytokine responses in inflammatory bowel disease." (PMID 37190070, 2023).
LINKED syndrome (3 papers, 2021 to 2023). "This approach is further illustrated in elegant work by Werner and colleagues, who showed that the deubiquitylating enzyme OTUD5 is mutated in a form of ID known as LINKED syndrome." (PMID 35212144, 2023). "This again provides an elegant molecular framework to explain the development of ID in LINKED syndrome patients with OTUD5 gene variants." (PMID 35212144, 2023). "LINKage-specific-deubiquitylation-deficiency-induced embryonic defects (LINKED) syndrome, arising from pathogenic OTUD5 variants, was recently reported as a new XLID with additional congenital anomalies." (PMID 33748114, 2021). "In conclusion, we described three living patients with OTUD5 missense variants associated with LINKED syndrome." (PMID 33748114, 2021).
liver cancer (3 papers, 2020 to 2025). An epithelial or non-epithelial malignant neoplasm that arises from the liver. "To further validate the OTUD5 expression in primary liver cancer, we assessed OTUD5 expression and its correlation with clinical features in another cohort of HCC patients (Cohort 2)." (PMID 32826889, 2020). "OTUD5 expression was significantly downregulated in the primary liver cancer tissues compared with that in the normal liver tissues (p < 0.05 by Fisher’s exact test)." (PMID 32826889, 2020). "Furthermore, the expression of OTUD5 was correlated with sex and tumor grade in patients with primary liver cancer." (PMID 32826889, 2020).
diabetic kidney disease (2 papers, 2024 to 2025). Progressive kidney disorder caused by vascular damage to the glomerular capillaries, in patients with diabetes mellitus. "The deubiquitinating enzymes UCH-L1, USP22, OTUD5, and USP14 act on PIRK3, TAK1, and SPAG5, respectively, and play a regulatory role in the pathophysiological process of diabetic kidney disease." (PMID 40225869, 2025).